PTX3 (pentraxin 3)
Diseases named in the same sentence as PTX3 in open-access papers (continued):
Sharing a sentence is not in itself a finding about the gene and the disease.
Arthritis (11 papers, 2010 to 2025). Inflammation of a joint. "Our findings suggest that higher anti-PTX3 antibody levels can help identify true active disease in RA patients with minimal objective signs of arthritis, particularly among seronegative RA patients." (PMID 39340807, 2025). "In a K/BxN serum-transfer arthritis model, PTX3 mRNA and protein levels were both elevated in the ankle joints of arthritic mice, and further increased in arthritic animals lacking matrix metallopeptidase 8, which had more severe disease." (PMID 31787987, 2019). "A lack of MMP-8 causes the aggravation of arthritis through promotion of inflammation by IL-1β and PTX3, inducing the maturation and activation of osteoclasts or enhancement of the inflammatory infiltrate by PROKR2 and IL-1β." (PMID 28445942, 2017). "CRP, ER, MCP-1 and PTX3 may play a significant regulatory role in improving arthritis." (PMID 34447637, 2021). "Recent evidence points to contrasting roles for PTX3 in bone pathophysiology: on one hand, it acts as a promoter of osteoblast differentiation and mineral matrix deposition; on the other, it supports osteoclastogenesis in inflammatory conditions, including arthritis and bone metastasis." (PMID 31787987, 2019). "As compared traditional biomarkers, PTX3 has been found to be a sensitive non-invasive biomarker of clinical arthritis activity in RA, indicating that ER, CRP and PTX3 may play a significant role in improving arthritis." (PMID 34447637, 2021). "Our results showed an increased PTX3 expression in mice lacking Mmp8 compared with wildtype mice, where it was also increased, indicating that PTX3 upregulation could have contributed to the higher arthritis severity in the knockout mice." (PMID 21190566, 2010).
chronic obstructive pulmonary disease (11 papers, 2014 to 2025). A chronic and progressive lung disorder characterized by the loss of elasticity of the bronchial tree and the air sacs, destruction of the air sacs wall, thickening of the bronchial wall, and mucous accumulation in the bronchial tree. "To date, polymorphisms in PTX3 have been reported in different clinical settings as a risk factor for invasive pulmonary aspergillosis in haematopoietic stem cell transplant recipients, solid organ transplants and chronic obstructive pulmonary disease." (PMID 36733397, 2022). "PTX3 expression is significantly elevated in patients with bacterial infections, including chronic obstructive pulmonary disease and community-acquired pneumonia." (PMID 40313930, 2025). "In patients with chronic obstructive pulmonary disease (COPD), levels of PTX3 in sputum samples are associated with bacterial infections and can potentially be a marker of exacerbation of the disease." (PMID 31031772, 2019). "Chronic obstructive pulmonary disease patients may also have elevated levels of Ptx3 in both plasma and BALF compared to healthy subjects." (PMID 36422015, 2022). "The association between serum pentraxin-3 (PTX-3) levels and chronic obstructive pulmonary disease (COPD) has been explored in several studies." (PMID 39151096, 2024).
Infertility (11 papers, 2016 to 2026). "In a mouse model, PTX3 expression is significantly increased in cumulus cells before ovulation and is associated with cumulus matrix formation, and PTX3 blockade in mice results in infertility." (PMID 37332766, 2023). "Previous reports asserted that deletion or reduction of Ptx3 and Gpx3 expression levels in mice results in the failure of oocyte fertilization and infertility." (PMID 34991678, 2022). "The mouse availability was further challenged by the infertility of female PTX3-/- mice; as a result, for this initial proof-of-principle study, we used only one time point for tissue collection." (PMID 29492210, 2018). "PTX3 has been shown to be important in ECM remodelling within the follicle leading to infertility in PTX3−/− mice." (PMID 28056989, 2017). "Finally, prospective studies evaluating PTX-3 as a predictive marker or therapeutic target in PCOS-related infertility are warranted." (PMID 41013753, 2025). "Whether this function of PTX3 therefore is of importance in the human testis, where fibrotic remodeling of the tubular wall typically occurs in infertility, remains to be shown." (PMID 27849015, 2016). "Medical treatments aimed at correcting expression defects of PTX3, VDR and other cumulus genes may emerge as a new approach to the treatment of PCOS-related infertility." (PMID 38167474, 2024).
injury (11 papers, 2011 to 2024). Damage inflicted on the body as the direct or indirect result of an external force, with or without disruption of structural continuity. "Research indicates PTX3 markedly elevates indices such as LVEF, LVFS, and LVAW thickness in d, as well as improves the E/A ratio and reduces the LVID, indicating that PTX3 has a certain improvement effect on systolic and diastolic dysfunction caused by septic myocardial injury." (PMID 38784395, 2024). "In analogy, we investigated whether PTX3 deficiency in the MSCs and/or at the endogenous level might impact the ability of MSCs to promote short- and long-term recovery from acid aspiration acute lung injury." (PMID 28265979, 2017). "PTX3 is a member of the pentraxin superfamily, which is rapidly produced and released by resident and innate immunity cells in response to kidney injury, and PTX3 levels were observed to rise as eGFR decreased." (PMID 35327386, 2022). "It has been shown that PTX3 can limit tissue damage in murine models of acute lung injury and ischemia/reperfusion-induced kidney injury by regulating neutrophil recruitment at inflamed sites." (PMID 34248970, 2021). "PTX3 is an acute-phase inflammatory mediator produced by different cell types that exerts protective effects in experimental acute lung injury, closely resembling those of MSCs." (PMID 28265979, 2017). "Both protective and detrimental effects of PTX3 have been described, such as in postischemic renal injury." (PMID 25855355, 2015). "Similarly, recent studies have demonstrated that the therapeutic effects of MSCs are indicated by the PTX-3 level in various in vivo models (e.g., wound healing, ischemic brain injury, and acute lung injury)." (PMID 34572070, 2021). "We only examined three time-points (i.e., 24 h and 1 and 2 weeks), which might have prevented us from description of other effects of WT-MSCs or PTX3−/−-MSCs in acid aspiration acute lung injury." (PMID 28265979, 2017). "Importantly, in a model of acid-induced acute lung injury, both exogenous PTX3 and endogenously released PTX3 administration suppress neutrophil recruitment." (PMID 23248627, 2012). "There is evidence suggesting that PTX3 may contribute to acute lung injury (ALI) during inflammation, and a correlation between PTX3 expression and the severity of the lung injury has been documented." (PMID 21423699, 2011). "Recognizing and rapidly diagnosing CNS infections in traumatic brain injury patients with extraventricular drainage is challenging due to symptomatology and elevated known CSF biomarkers affected by trauma itself, and analysis of CSF PTX3 in such a group of patients would be interesting." (PMID 36862691, 2023). "On the other hand, PTX3 locally released by activated leukocytes may impair leukocyte rolling on endothelium, thus attenuating the recruitment of neutrophils, regulating inflammation, and reducing tissue damage in murine models of acute lung injury, pleurisy, and mesenteric inflammation." (PMID 33679758, 2021).
ischemia (11 papers, 2010 to 2024). A hypoperfusion of the BLOOD through an organ or tissue caused by a PATHOLOGIC CONSTRICTION or obstruction of its BLOOD VESSELS, or an absence of BLOOD CIRCULATION. "The main finding is that 10 genes (Clec5a, CD14, Fgr, Hck, Anxa1, Lgals3, Irf1, Lbp, Ptx3, Serping1) may represent key molecular links underlying acute activation of immune cells in the hippocampus in response to experimental ischemia." (PMID 34944656, 2021). "Accordingly, Ptx3 upregulation is observed in mice under various experimental neuroinflammatory conditions, including neurotrauma, ischemia, limbic seizure and autoimmune encephalomyelitis." (PMID 36012705, 2022). "For instance, PTX3 was found to limit postischemic acute and chronic kidney injury, but exacerbate tissue inflammation after intestinal ischemia and reperfusion in mice." (PMID 32938460, 2020). "Previous studies described Pentraxin-3 as a factor that promotes recovery in neural tissue after ischemia." (PMID 32183876, 2020). "Nonetheless, blocking PTX3 action attenuates tissue inflammation and cytokine production after intestinal ischemia and reperfusion injury." (PMID 31744201, 2019). "Cerebral inflammation or ischemia was induced in WT and PTX3 KO mice via intrastriatal LPS injection or by transient middle cerebral artery occlusion (MCAo) respectively." (PMID 31602423, 2019). "Consistent with our studies, the elevation in vascular permeability by tissue injury after intestinal ischemia and reperfusion was dramatically repressed in PTX3 knockout mice." (PMID 28489600, 2017). "On the other hand, a detrimental role was also ascribed to PTX3 in a mouse model of ischemia followed by reperfusion of the superior mesenteric artery." (PMID 20920344, 2010). "Ischaemia-modified albumhumin (IMA), serum D-dimer (s-DD), heat shock protein-70 (hsp-70), Pentraxin-3 (PTX3), and c-reactive protein (CRP) each showed the most promise, with p-values for the difference between OT and control groups achieving ≤ 0.001." (PMID 39519217, 2024).
lupus nephritis (11 papers, 2011 to 2025). Glomerulonephritis in the context of systemic lupus erythematosus. "The associations between anti-PTX3 auto-antibodies and clinicopathological parameters in lupus nephritis were further analyzed." (PMID 28393653, 2017). "Herein, we detected the prevalence of anti-PTX3 auto-antibodies in a large lupus nephritis cohort and further analyzed the associations between them and clinicopathological features." (PMID 28393653, 2017). "Previous studies, including ours, indicated that serum PTX3 level was closely associated with disease activity and severity of lupus nephritis." (PMID 28393653, 2017). "Furthermore, we did comparisons of associations between renal injury indices and serum PTX3 level and other 2 conventional biomarkers, anti-ds-DNA antibody and C3 level, in lupus nephritis." (PMID 26817892, 2016). "As PTX3 could be both an enhancement and inhibition of the inflammatory process depending on the way which it regulated the complement activation, the “double edged roles” of PTX3 on tubulointerstitial inflammation and the signaling mechanisms underlying this in lupus nephritis need further studies." (PMID 26817892, 2016). "In lupus nephritis higher u-PTX-3 levels were observed in patients with active disease, and in ANCA-associated vasculitis u-PTX-3 seemed to reflect disease activity better than CRP." (PMID 40008348, 2025). "A previous urine (u) PTX-3 study among patients with lupus nephritis found increased levels in patients with active versus inactive disease." (PMID 40008348, 2025). "Male patients with lupus nephritis was more likely to have anti-PTX3 auto-antibodies than females (31.6% (12/38) versus 13.3% (21/158), p = .01)." (PMID 28393653, 2017). "The serum levels of anti-PTX3 auto-antibodies were negatively correlated with the amount of proteinuria in lupus nephritis patients (r= −.143, p = .47)." (PMID 28393653, 2017). "This study is to investigate the prevalence of anti-PTX3 auto-antibodies and their clinical significance based on a large Chinese lupus nephritis cohort." (PMID 28393653, 2017). "The positive ratio of anti-PTX3 auto-antibodies in lupus nephritis was significantly higher than that in normal controls (19.4% (38/196) versus 2% (2/100), p < .001)." (PMID 28393653, 2017). "The serum levels of anti-PTX3 auto-antibodies were negatively correlated with proteinuria in lupus nephritis (r = −.143, p = .047)." (PMID 28393653, 2017). "More interestingly, we found that the positive ratio of anti-PTX3 auto-antibodies was higher in male lupus nephritis than females." (PMID 28393653, 2017). "Urinary PTX3 levels were found elevate significantly in patients with active lupus nephritis than that in remission and normal controls." (PMID 26817892, 2016). "Intense staining for PTX3 was mainly observed in the tubulointerstitial areas of lupus nephritis patients." (PMID 26817892, 2016). "The urinary PTX3 levels were significantly higher in active lupus nephritis patients compared with patients in remission and normal controls (P = 0.011, P = 0.008, respectively)." (PMID 26817892, 2016). "In order to identify the cell types that contribute to the production of PTX3 in lupus nephritis, kidney biopsies were double stained for several markers of renal cells and PTX3 by immunofluorescence." (PMID 26817892, 2016). "There were significant correlations between urinary and serum PTX3 levels in patients with lupus nephritis (r = 0.431, P = 0.006)." (PMID 26817892, 2016). "Serum PTX3 levels of 15 lupus nephritis patients in remission decreased significantly compared with that in active phase." (PMID 26817892, 2016). "The PTX3 expressions in renal tissues were investigated in 35 patients with active lupus nephritis by immunohistochemistry." (PMID 26817892, 2016). "The aim of this study was to investigate the serum and urine levels of PTX3, and the expression of PTX3 in renal tissues in lupus nephritis patients from a large Chinese cohort." (PMID 26817892, 2016).
lupus nephritis (continued). "This study was to investigate the circulating and local levels of PTX3 in lupus nephritis from large North Chinese multicenter cohorts, and their correlation with clinical and histopathological parameters was studied." (PMID 26817892, 2016). "In contrast, histomorphological and functional parameters of lupus nephritis remained unaffected by the Ptx3 genotype." (PMID 21637713, 2011). "Anti-PTX3 antibodies was able to prevented lupus nephritis progression." (PMID 39666228, 2024). "In addition, the deposition degree of PTX3 in lupus nephritis (LN) is also related to the pathological degree." (PMID 35739102, 2022). "Moreover, the serum levels of anti-PTX3 Abs were negatively correlated with proteinuria in lupus nephritis." (PMID 33664737, 2020). "This suggests that anti-PTX3 Abs might inhibit the secretion of nephritogenic Abs in lupus nephritis." (PMID 33664737, 2020). "Our previous study demonstrated that circulating levels and renal deposition of PTX3 were increased in active lupus nephritis patients, which suggested that PTX3 might be involved in the pathogenesis of lupus nephritis." (PMID 28393653, 2017). "Thus, lupus nephritis patients in our study were divided into two groups according to their serum anti-PTX3 auto-antibodies and PTX3 levels." (PMID 28393653, 2017). "Second, several studies showed that the long-term survival and renal outcomes were better in male lupus nephritis patients compared with females which might be in consistence with our speculation that anti-PTX3 auto-antibodies could be protective." (PMID 28393653, 2017). "The role of anti-PTX3 auto-antibodies in the pathogenesis of lupus nephritis remained unclear." (PMID 28393653, 2017). "Second, the mechanic investigations by which anti-PTX3 auto-antibodies could modify disease course, especially its immunologic characteristics in lupus nephritis, were needed in the future." (PMID 28393653, 2017). "In conclusion, our study showed that the significantly increased circulating and local PTX3 levels could be found in patients with active lupus nephritis and PTX3 might be a biomarker for the disease progression, especially tubulointerstitial injury." (PMID 26817892, 2016). "Furthermore, in renal histopathology evaluation, serum PTX3 levels were the highest in patients with class IV lupus nephritis." (PMID 26817892, 2016). "PTX3 staining was mainly observed in tubulointerstitial areas of patients with lupus nephritis, and immunofluorescence study showed that PTX3 could colocalize with fibroblast in interstitium." (PMID 26817892, 2016). "The exact role of PTX3 in the pathogenesis of lupus nephritis needs further explorations." (PMID 26817892, 2016). "The urinary PTX3 levels were significantly higher in active lupus nephritis group compared with lupus nephritis patients in remission and normal controls (1.929 (0.001–112.506) vs. 0.068 (0.001–3.031) ng/mg Cr, P = 0.011; 1.929 (0.001–112.506) vs. 0.023 (0.002–1.143) ng/mg Cr, P = 0.008)." (PMID 26817892, 2016). "Circulating and local PTX3 levels were significantly increased in patients with active lupus nephritis and might be a biomarker for the disease progression, especially of tubulointerstitial injury." (PMID 26817892, 2016). "Interestingly, recent studies indicated that anti-C-reactive protein (CRP) auto-antibodies and anti-PTX3 autoantibodies also correlated with histopathological activity and disease activity in lupus nephritis." (PMID 23510032, 2013). "Thus, the correlations between C1q, CRP, PTX3 and its auto-antibodies in the formation of immune complex in lupus nephritis need further investigation." (PMID 23510032, 2013). "Thus, we speculated that the expression of PTX3 in lupus nephritis might be different and serve as a biomarker of local inflammation." (PMID 26817892, 2016). "Thus, we raised the possibility that renal locally produced PTX3 might be involved in the progression of lupus nephritis." (PMID 26817892, 2016).